CRHR2 (corticotropin releasing hormone receptor 2)
Description:
G protein-coupled receptor for CRH, UCN, UCN2 and UCN3 stress hormones, which plays a central role in whole body adaptation to stress. Has highest affinity for UCN, and much lower affinity for CRH, UNC2 and UCN3. Ligand binding causes a conformation change that triggers signaling via guanine nucleotide-binding proteins (G proteins) and downstream effectors, such as adenylate cyclase. CRHR2 is coupled to G(s) G protein (GNAS), mediating activation of adenylate cyclase activity and production of cAMP. CRHR2-dependent signaling is a primary mediator of the neuroendocrine, autonomic (fight-or-flight) and behavioral responses to stress, acting as a key regulator of adaptation by activating the hypothalamus-pituitary-adrenal axis, leading to corticotropin hormone (ACTH) production (By similarity).
Synonyms: CRF2; CRF-RB; HM-CRF; CRFR2
Tractability: Small molecule: a structure with a bound ligand is known. Antibody: UniProt places it where antibodies can reach, with high confidence; its Gene Ontology location is reachable by antibodies, with high confidence; UniProt predicts a signal peptide or a membrane-spanning region; the Human Protein Atlas places it where antibodies can reach. PROTAC: a small molecule that binds it is known.
Target class: Corticotropin releasing factor receptor; Membrane receptor; Family B G protein-coupled receptor; Peptide receptor (family B GPCR)
Gene: Protein-coding gene on chromosome 7 (30,651,444 to 30,700,129, reverse strand). Ensembl gene ENSG00000106113.
Subcellular location: Cell membrane
Subcellular location (Human Protein Atlas): Plasma membrane; Predicted to be secreted
Pathways (Reactome):
Signal Transduction: Class B/2 (Secretin family receptors); G alpha (s) signalling events
Metabolism of proteins: Synthesis, secretion, and deacylation of Ghrelin
Gene Ontology:
Molecular function: corticotrophin-releasing factor receptor activity; G protein-coupled peptide receptor activity; protein binding; corticotropin-releasing hormone receptor activity; peptide hormone binding; G protein-coupled receptor activity; transmembrane signaling receptor activity
Biological process: adenylate cyclase-activating G protein-coupled receptor signaling pathway; adenylate cyclase-modulating G protein-coupled receptor signaling pathway; energy homeostasis; general adaptation syndrome; long-term synaptic potentiation; positive regulation of corticotropin secretion; cell surface receptor signaling pathway; cellular response to corticotropin-releasing hormone stimulus; G protein-coupled receptor signaling pathway; hormone-mediated signaling pathway
Cellular component: plasma membrane; axon terminus; dendrite; membrane
Genetic constraint (gnomAD): Loss-of-function variants: 53 observed, 54.57 expected, observed/expected ratio (o/e) 0.97, 90% interval 0.78 to 1.22. The upper end of that interval is the gene's LOEUF score, 1.22, which puts it in group 5 of 6, group 1 being the genes least tolerant of losing a copy. Missense variants: 532 observed, 527.98 expected, observed/expected ratio (o/e) 1.01, 90% interval 0.94 to 1.08. Synonymous variants: 213 observed, 206.27 expected, observed/expected ratio (o/e) 1.03, 90% interval 0.92 to 1.16.
Homologues: Orthologues: chimpanzee CRHR2 (93% identical), macaque CRHR2 (91% identical), pig CRHR2 (91% identical), dog CRHR2 (90% identical), rabbit CRHR2 (89% identical), guinea pig CRHR2 (88% identical), rat Crhr2 (88% identical), mouse Crhr2 (87% identical), tropical clawed frog crhr2 (79% identical), zebrafish CRHR2 (70% identical). Paralogues in human: CRHR1 (68% identical), PTH1R (26% identical), PTH2R (25% identical), VIPR1 (25% identical), CALCR (24% identical), GLP1R (24% identical), SCTR (24% identical), VIPR2 (24% identical), ADGRL3 (23% identical), GCGR (23% identical), ADGRL1 (23% identical), CALCRL (23% identical), and 30 more.
Diseases named in the same sentence as CRHR2 in open-access papers:
CRHR2 is named in the same sentence as 90 diseases in open-access papers, as found by Europe PMC text mining. Sharing a sentence is not in itself a finding about the gene and the disease. The quoted sentences say what the papers report.
Anxiety (79 papers, 2007 to 2025). Intense feelings of nervousness, tension, or panic often arise in response to interpersonal stresses. "Crhr2 upregulation can also be linked to anxiety, as urocortin 2 (a CRHR2 agonist) induced anxiety-like behavior, when injected into the medial amygdala in rats." (PMID 37989901, 2024). "The results show a more complex modulating rolefor the CRH system than the conventional wisdom, whereCRHR1 causes anxiety and CRHR2 mediates recovery afterstress." (PMID 34901719, 2021). "CRHR2 down-regulation may be associated with the same effects seen in the CRHR2-knockout mice which manifested stressed and anxiety-like behavior." (PMID 36077219, 2022). "In the brain, CRHR1 stimulation causes anxiety, but CRHR2 stimulation induces anxiolysis." (PMID 26808377, 2016). "Whereas, in LSi, projections from corticotropin-releasing hormone receptor 2 (CRHR2) neurons to anterior hypothalamic nucleus (AHN) mediated anxiety potentiation." (PMID 41208898, 2025). "For example, CRHR2 knockout male and female mice exhibit increased anxiety in the EPM where mice spent less time in and entered the open arms less frequently." (PMID 39684893, 2024). "In a recent study, the researchers found that a deficiency of CRHR2 caused HPA axis dysfunction and induced anxiety in zebrafish." (PMID 39684322, 2024). "The CRHR2 gene is expressed in the brain; Crhr2 knockout mice show reduced stress response, hypersensitivity to stress, and anxiety behavior." (PMID 38927393, 2024). "Our results indicate the importance of CRHR2 signaling in anxiety-like behavior and regulation of the stress response." (PMID 39595978, 2024). "Animals with CRHR2 knockout or that of its ligands (Ucn2 KO and Ucn3 KO) display increased anxiety, corticosterone response, and impaired stress recovery." (PMID 39595978, 2024). "In conclusion, to the best of our knowledge, this is the first study demonstrating that a single intranasal application of the CRHR2 agonist Ucn3 has the potential to prevent the development of anxiety-like behaviors in an SPS animal model of PTSD." (PMID 39595978, 2024). "CRHR2−/− mice were found to have anxiety-like behaviors and be hypersensitive to stress, and the CRHR2 locus in humans (7p21-p15) has been linked to T2D and MDD." (PMID 36077219, 2022). "A subset of LS neurons that express Crhr2 (LSCrhr2) has been shown to mediate persistent stress-induced anxiety behavior." (PMID 36028570, 2022). "In contrast to CRHR1, the role of CRHR2 activation inthe manifestation of anxiety and depression is less clear, andthere are two theories trying to explain the CRHR2 involvement in the CRH behavioral effects." (PMID 34901719, 2021). "Crhr1/Crhr2 double knockout mice display sexually dimorphic HPA axis stress responses: female mice have decreased anxiety-like behavioral responses, whereas male mice show increased anxiety-like behavior." (PMID 32244319, 2020). "This upregulation of CRHR2 mRNA level possibly refers to an anxiolytic effect mediated by CRHR2 in buffering the SPS-induced conditioned anxiety." (PMID 30898126, 2019). "CRHR2 is highly expressed in the pituitary and is densely populated in brain structures involved in anxiety, fear, and arousal, such as the bed nucleus of the stria terminalis (BNST), a subregion of the extended amygdala that regulates the HPA axis." (PMID 29953524, 2018). "This notion is supported by the fact that statistical analysis of stress, anxiety, and depression including CRHR2 genotypes with group (IBS patients vs. controls) showed significant differences." (PMID 26808377, 2016). "Generally, CRHR1 activation, increases anxiety-like behavior, whereas activation of CRHR2 suppresses behavioral indicators of anxiety." (PMID 26318631, 2015). "Nes-Cre:Errβlox/lox mice lack Errβ in the hindbrain and have decreased expression of Crh, Crhr2 and Npy, suggesting that neuromodulators involved with the acoustic startle response reside in the hindbrain to modulate stress and anxiety." (PMID 24053666, 2013).
Anxiety (continued). "The EPM test was performed to examine whether CRHR2 agonist (Ucn2 or Ucn3) treatment could prevent the development of anxiety-like behavior in the SPS animals compared to the vehicle-treated ones." (PMID 39595978, 2024). "CRHR2 appears to play a role in reducing anxiety-like behaviour, and the downregulation of CRHR2 in loperamide-treated female rats may contribute to the anxiogenic effects seen in the behavioural tests." (PMID 39684893, 2024). "As HPA axis activation has been implicated in both CKD and anxiety, the expression of arginine vasopressin (Avp), corticotropin-releasing hormone (Crh), and CRH receptor 1 (Crhr1) and 2 (Crhr2) genes was determined in the amygdala, followed by analysis of protein expression." (PMID 37989901, 2024). "For instance, CRH, secreted from the central amygdala, binds to the basolateral amygdala CRHR1 and CRHR2 and may modulate stress-emotional memories and anxiety." (PMID 37508942, 2023). "Interestingly, NaB treatment contributed to the regulation of HPA axis (such as corticosterone as well as CRHR2) and improvement of anxiety and social deficit behaviors in LPS-exposed offspring." (PMID 37358267, 2023). "In addition, UCN3/CRHR2 possesses a variety of biological effects in the regulation of stress and anxiety, as well as stimulating sympathetic outflow, which was characterized by increased thermogenesis of BAT and upregulated Ucp1 in BAT." (PMID 31379744, 2019). "Moreover, CRHR2 might have a regulatory function in response to CRHR1 stimulation of the HPA axis or anxiety, and CRHR2 played an important regulatory role in the process of visceral pain signaling." (PMID 37435647, 2023). "Co-expression with fear-associated genes Crh, Crhr1, and Crhr2 across crude brain regions revealed that the metabolic receptor set correlated mostly in areas that are not often associated with anxiety, i.e., midbrain CRH expressing neurons, as present in the superior colliculus and nucleus ruber." (PMID 30210279, 2018). "Chronic variable stress in the third week of pregnancy in rats leads to increased anxiety-like behavior in the elevated-plus-maze (EPM) in young adult offspring and is associated with increased CRH and CRHR1 in the amygdala of female offspring and CRHR2 expression in offspring of both sexes." (PMID 26082698, 2015). "In our gene expression analysis, significant upregulations of Crh, Crhr1, and Crhr2 were observed in the amygdala in the CKD group, which is in accordance with the development of anxiety-like behavior." (PMID 37989901, 2024). "CRH, released by the bed nucleus of the stria terminalis (BnST), modulates stress-related anxiety via CRHR1 located in the nucleus accumbens and CRHR2." (PMID 37508942, 2023). "Since these rats also exhibit anxiety differences and the QTL for alcohol preference largely overlaps with Anxrr16, the Crhr2 gene can be considered as a promising candidate for our main anxiety-related QTL." (PMID 36056863, 2023). "CRHR2 plays a role in counteracting the effect of CRHR1 activation, which induces anxiety-like behavior and stress response." (PMID 37358267, 2023). "CRHR2 down-regulation may also lead to hypercortisolemia via an inappropriately high-normal CRH and ACTH, via CRHR1 pituitary activation, and simultaneously drive central and peripheral catecholamine secretion, which can further mediate the anxiety-causing and hyperglycemic effects." (PMID 36077219, 2022). "CRHR2 is highly expressed in the posterior BST (BSTp), and optogenetic activation of CRHR2 neurons in the BSTp reduced anxiety-like behaviors in mice in the EPM and OF tests, while inhibition increased anxiety-like behaviors." (PMID 33867924, 2021). "The knockdown of the corticotropin-releasing hormone receptor 2 (CRH2), known to phosphorylate CREB, resulted, as expected, in reduced pCREB and, additionally, higher anxiety levels." (PMID 25505876, 2014).
Anxiety (continued). "Of the two receptors in this system (CRHR1 and CRHR2), overactivity of CRHR1 in anxiety and depression has been a consistent finding in animal studies." (PMID 22950410, 2012). "CRHR2 is one of the receptors through which corticotropin-releasing hormone (CRH) acts to regulate stress responses and plays an important role in the development of anxiety and depression." (PMID 39684893, 2024). "The most commonhypothesis – CRHR2 activation is responsible for providingphysiological and psychological homeostasis and counteractsthe initial effects of CRHR1 activation, which induce stressresponse and anxiety-like behavior (Bale, Vale, 2004)." (PMID 34901719, 2021). "Male Crhr2-/- mice are hypertensive, have increased ACTH and glucocorticoid release, i.e., are hypersensitive to the HPA axis-mediated stress responses, and show increased anxiety-like behavior." (PMID 32244319, 2020). "Interestingly, among the anxiety- and depression-related DEGs, we found the upregulation of Bcl3, C3, Gpat3, and Tnf in the AMY as well as the increased expression of Crhr2, Nant, Sar1a, and Tgif1 and the decreased expression of Ier2, Il12a, Nrep, and Tnfrsf25 in the ACC." (PMID 33898422, 2021). "Especially, we discovered that the group with one of four haplotypes (T-T-T-T, C-T-T-T, C-C-T-T, and T-C-T-T) in CRHR2 showed a significantly lower score in perceived stress, anxiety, and depression in comparison with the group that did not have one of these haplotypes." (PMID 26808377, 2016). "Our results show increased Crh and Crhr1 (but not Crhr2) gene expression in the CeA in FD rats, supporting a potential role for augmented CRH signaling in the pathogenesis of depression and anxiety in this model." (PMID 33591956, 2021). "However, it could be relevant to the evidences that CRHR1 exhibits higher affinity to CRH than CRHR2 and the lack of CRHR1 leads to a greater influence to anxiety." (PMID 30898126, 2019).
depression (30 papers, 2011 to 2025). "A few studies have investigated the potential involvement of CRHR2 in depressive disorders, finding a positive correlation of some alleles with MDD or its mediated resistance to pharmacological treatment." (PMID 38927393, 2024). "CRHR2−/− mice are hypersensitive to stress, and the CRHR2 locus has been linked to type 2 diabetes and depression." (PMID 36077219, 2022). "Although the families were primarily ascertained for type 2 diabetes, depression-risk variants showed higher significance than type 2 diabetes-risk variants, implying CRHR2 has a stronger role in depression-risk than type 2 diabetes-risk." (PMID 36077219, 2022). "In humans, the CRHR2 locus 7p21-p15 has been linked to depression, bipolar disorder, obesity, T2D, and increased HDL and triglyceride levels." (PMID 36077219, 2022). "CRHR2 polymorphisms have been associated with increased risk of suffering major depression with borderline significance and with a worse overall response to citalopram (SSRI)." (PMID 25086452, 2014). "A latter-day study in Italian families burdened with TMD2 and MDD indicated that CRHR2 gene pleiotropism might underlie the diabetes and depression comorbidity." (PMID 37972981, 2023). "CRHR2 is for the first time linked to/in linkage-disequilibrium/association with depression-type 2 diabetes comorbidity and may underlie the shared genetic pathogenesis via pleiotropy." (PMID 36077219, 2022). "Analyzing 12 SNPs of the CRHR2 and CRHR1 genes, a Japanese study revealed that the T/A haplotype of rs7209436-rs110402 is significantly associated with major depression." (PMID 40869374, 2025). "Mutaz Amin's team has successively revealed the role of nuclear receptor subfamily 3 Group C member (NR3C1) Gene, corticotropin‐releasing hormone receptor 2 (CRHR2) Gene, and Melanocortin Receptor Genes in the comorbidity of familial diabetes and depression." (PMID 40820550, 2025). "This network consisted of a number of molecules previously reported to be associated with depression (according to a PubMed search), such as CYP3A5, VAMP2, CSGALNACT1, CASP8, CRHR2, PKD2, and OXT." (PMID 26728011, 2016). "A few studies show a correlation of the CRHR2 gene with depressive disorders." (PMID 38927393, 2024). "Several CRHR2 SNPs have been reported to be associated with PTSD in EA women, and with major depressive disorder (MDD) in Japanese but none of them is in LD with SNP rs255105 indicated in the current study." (PMID 29953524, 2018). "Furthermore, CRHR2 and CRHR1 participated in the co-expression network for healthy controls only, indicating their decreased connectivity with other genes in depression." (PMID 26728011, 2016).
Obesity (12 papers, 2006 to 2024). Accumulation of substantial excess body fat. "In subjects with extreme early-onset obesity, three missense mutations were found in CRHR2 (Glu220Asp, Val240Ile and Val411Met)." (PMID 17183713, 2006). "Crhr2 knockout mice have arterial hypertension and reduced sustained hypophagia; thus, CRHR2 variants might contribute to hypertension and obesity." (PMID 38927393, 2024). "For example, at the Crhr2 gene, which plays roles in lipid and cholesterol metabolism and has been implicated in obesity, BL6 had significant changes on the American diet which were restored to standard-diet levels with GW4064 treatment, while NOD had no change in any diet or treatment group." (PMID 37871105, 2023). "Interestingly, UCN3 and CRHR2 are proposed as potential anti-obesity targets owing to their co-location with quantitative trait loci for obesity on chromosome 10p15.116." (PMID 34341463, 2021). "None of the markers in CRHR2 was associated with obesity-type traits in cattle, which is consistent with findings in human." (PMID 17183713, 2006). "The authors concluded that mutations in the coding sequence of the CRHR2 gene are unlikely to be a common monogenic cause of early-onset obesity." (PMID 17183713, 2006). "None of the genotyped variants in genes for monogenic obesity reached genome-wide significance in our GWAS, although several variants in CRHR1, CRHR2, MCHR1, MC3R, MC4R and POMC were nominally associated." (PMID 23251661, 2012).